FABP4 (fatty acid binding protein 4)
Diseases named in the same sentence as FABP4 in open-access papers (continued):
Sharing a sentence is not in itself a finding about the gene and the disease.
atherosclerosis (continued). "Fatty acid-binding protein 4 (FABP4) is secreted from adipose tissue and acts as an adipokine, and an elevated circulating FABP4 level is associated with metabolic disorders and atherosclerosis." (PMID 33597568, 2021). "Recent studies using experimental models demonstrated the possibility of a new strategy for treating metabolic diseases including diabetes mellitus, atherosclerosis and vascular injury by targeting serum FABP4 with a monoclonal antibody to FABP48,11,12." (PMID 33597568, 2021). "SREBP1 and FABP4 are involved in regulating many metabolic pathways, such as those related to type 2 diabetes, atherosclerosis, and hepatic lipid accumulation." (PMID 34768813, 2021). "Elevated circulatory FABP-4 levels were correlated with hypertension, obesity, atherosclerosis, left ventricular diastolic dysfunction, heart failure, and DMT2." (PMID 34680583, 2021). "Targeting RBP4, FABP4 or their signaling pathway to treat diabetes or atherosclerosis has been a profuse topic for the last few years." (PMID 34638803, 2021). "Obese individuals carrying a T-87C polymorphism in the FABP4 gene, which reduces transcription of FABP4, have decreased dyslipidemia and atherosclerosis." (PMID 32856199, 2020). "Conclusion—We discovered a novel pathogenic role of FABP4 in MNC activation and endothelial dysfunction in atherosclerosis." (PMID 33287461, 2020). "Fatty acid binding protein 4 (FABP4) is mainly expressed by adipocytes and is known to play a significant role in the development of atherosclerosis." (PMID 32887447, 2020). "FABP4 plays multiple and important roles in metabolic and cardiovascular diseases, such as diabetes mellitus, cardiac dysfunction and atherosclerosis." (PMID 32896039, 2020). "Rodríguez-Calvo reported that FABP4 was a useful biomarker in atherosclerosis and coronary artery disease and was directly related to cardiac alterations." (PMID 32075656, 2020). "Previous studies investigated the correlation between FABP4 and atherosclerosis, as well as coronary artery disease." (PMID 30969942, 2019). "Abnormalities in the level of FABP4 have been correlated with the development of adiposity, oxidative stress, and atherosclerosis." (PMID 30857223, 2019). "Recent studies in models of atherosclerosis have demonstrated that local serum levels of FABP4 within the aorta correlate with disease severity." (PMID 30705117, 2019). "In many studies FABP4 has been shown to play a role in the development of atherosclerosis by activating an inflammatory response through inhibition of endothelial nitric oxide synthetase in smooth muscle cells." (PMID 31651119, 2019). "FABP4 has recently been shown to be associated with an increased cardiometabolic risk, and previous studies have reported both clinical and experimental evidence that FABP4 is a relevant factor in atherosclerosis and CAD." (PMID 31234795, 2019). "Starting with lipid metabolism, HHcy-induced atherosclerosis in ApoE-/- mice is mediated by decreased DNA methylation and increased fatty acid-binding protein 4 (FABP4) expression." (PMID 31252610, 2019). "FABP4 plays a crucial role in mediating the endoplasmic reticulum stress observed in macrophages upon lipotoxic signal exposure, which contributes to atherosclerosis, inflammation, and perhaps plaque vulnerability." (PMID 30857223, 2019). "Considerable evidence suggested a link between FABP4 and ER stress in disease models including diabetes, atherosclerosis and kidney disease, etc.." (PMID 30135658, 2018). "The protective effect of the deletion of FABP4 on atherosclerosis is related to the actions in macrophages, which has been confirmed by the bone marrow transplantation researches." (PMID 30142969, 2018). "Compared to mice with a single deficiency of FABP4 or FABP5, the combined deficiency of FABP4 and FABP5 better improves insulin sensitivity and protects against atherosclerosis and type II diabetes." (PMID 30142969, 2018).
atherosclerosis (continued). "Fatty acid-binding protein 4 (FABP4), also named as adipocyte P2 (aP2) or adipocyte-FABP (A-FABP), is a novel adipokine involved in energy balance, ER stress and inflammation in diabetes, atherosclerosis, and kidney diseases." (PMID 30135658, 2018). "FABP4 is also capable of resisting the development of atherosclerosis and improving the sensitivity of insulin." (PMID 30519272, 2018). "FABP4 possessed a well-established role in the pathogenesis of diabetes and atherosclerosis, however, the effect of FABP4 in rhabdomyolysis-induced AKI has not been determined." (PMID 30135658, 2018). "Genetic or chemical inhibition of FABP4 alleviates macrophage ER stress and protects against atherosclerosis in an animal model." (PMID 30002403, 2018). "Fatty acid-binding protein 4 (FABP4) is a key mediator of endoplasmic reticulum (ER) stress and apoptosis in diabetes and atherosclerosis." (PMID 35541316, 2018). "BMS309403 is a biphenyl azole inhibitor specifically designed to target FABP4 and it protected against severe atherosclerosis and type 2 diabetes." (PMID 29340091, 2017). "The impact of Fabp4 on atherosclerosis is mainly due to the role of this molecule in macrophages and dendritic cells." (PMID 29064389, 2017). "A recent study has demonstrated that suppression of FABP4 protects mice against atherosclerosis and compromises the inflammatory responses of macrophages." (PMID 28331434, 2017). "Numerous studies have elucidated the roles of FABP4 in body-weight control, glucose and lipid metabolism, β-cell function and the pathogenesis of atherosclerosis." (PMID 26823558, 2016). "In atherosclerosis, FABP4 expression was reported to correlate with plaque instability in a study using endarterectomy samples collected from patients with symptomatic and asymptomatic carotid stenosis." (PMID 24732569, 2014). "It has been shown that a small-molecule specific FABP4 inhibitor would be a novel strategy to prevent and treat type 2 diabetes mellitus and atherosclerosis." (PMID 25506691, 2014). "Our present study using gene transcript profiling and protein measurements in circulating blood cells from an experimental model, demonstrate FABP4 to be a robust marker of the extent of atherosclerosis." (PMID 23387955, 2013). "FABP4 expression in macrophages plays a specific and independent role in experimental atherosclerosis." (PMID 23642261, 2013). "As FABP4 was primarily expressed in macrophages within the atherosclerotic lesion, we examined the ability of several stimuli with relevance to atherosclerosis to modify FABP4 expression in THP-1 monocytes/macrophages." (PMID 22174896, 2011). "FABP4 promotes lipolysis and therefore contributes to the accumulation of lipids and the development of harmful secondary conditions such as type 2 diabetes and atherosclerosis." (PMID 40234265, 2025). "FABP4 is a well‐known inflammatory regulator involved in various inflammatory diseases such as ischemic stroke, non‐alcoholic steatohepatitis, and atherosclerosis by activating the JNK, NF‐κB, and JAK2/STAT2 signaling pathways in macrophages." (PMID 38884133, 2024). "Apolipoprotein-E-deficient mice with FABP4 deficiency did not develop atherosclerosis from a high-cholesterol diet." (PMID 37794302, 2024). "Hypomethylation of FABP4 accelerates lipid accumulation in homocysteine-induced (Hcy) atherosclerosis, implying that FABP4 may be involved with foam cell formation and macrophage inflammation." (PMID 38698167, 2024). "Moreover, recent research on the effect of FABP4 in macrophages has shown that macrophages expressing FABP4 often induce inflammation and play an important role in the development of atherosclerosis, COVID-19, and cancers." (PMID 39353883, 2024). "Taken together, oridonin might have potential to protect against atherosclerosis by modulating the formation and inflammatory response in foam macrophages through FABP4/PPARγ signalling." (PMID 37905351, 2023).
atherosclerosis (continued). "Our results showed that oridonin inhibited atherosclerosis, as it performed double duty on lipid modulation and anti‐inflammation properties in macrophages via fatty acid binding protein 4 (FABP4)/peroxisome proliferator‐activated receptor gamma (PPARγ) pathway." (PMID 37905351, 2023). "Another molecule, fatty acid-binding protein 4 (FABP4), has recently been shown to play a role in atherosclerosis and coronary artery disease, and it has been directly related to cardiac alterations such as left ventricular hypertrophy (LVH) and both systolic and diastolic cardiac dysfunction." (PMID 37298029, 2023). "A direct relationship has been shown between FABP-4, diabetes, and atherosclerosis in mice." (PMID 38024104, 2023). "After overlapping the 431 putative targets of atorvastatin with 15 common pathogenic genes between atherosclerosis and NSCLC, then find 4 genes (MMP9, MMP12, CD36, and FABP4) were identified as potential therapeutic targets of atorvastatin for atherosclerosis and NSCLC." (PMID 37978381, 2023). "FABP-4 is an emerging adipokine that plays an important role in the development of metabolic syndrome and type 2 diabetes as well as complications resulting from these disorders, including atherosclerosis." (PMID 38024104, 2023). "Considering the similar features between atherosclerosis and AS, we propose that FABP4 may play an important role in the pathophysiology of AS and, consequently, may be postulated as a novel therapeutic target." (PMID 35955575, 2022). "Therefore, the aim of the present work was to investigate the effect of FABP4 on regulating the JAK2/STAT2 pathway in macrophage inflammation in atherosclerosis." (PMID 34725437, 2022). "Increased macrophage FABP4 expression is linked to atherosclerosis, and co-treatment of statins and Dex, but not Dex alone, exacerbated high-fat diet-induced atherosclerosis in apoE-deficient mice." (PMID 36054185, 2022). "Moreover, IL-17A was involved in accelerating atherosclerosis via enhancing FABP4-mediated endoplasmic reticulum (ER) stress in macrophages." (PMID 36311201, 2022). "Another study in an animal model revealed that benzbromarone inhibits both URAT1 and FABP4, which indicates that benzbromarone may be a potential candidate for the treatment of DM and atherosclerosis." (PMID 35055342, 2022). "It has been suggested that increased serum concentrations of FABP-4 may occur in patients with diabetes mellitus type 2, obesity, arterial hypertension, and nonalcoholic fatty liver disease or atherosclerosis." (PMID 36144237, 2022). "However, recent studies reported that inhibition of FABP4 has a potentially significant effect against diabetes mellitus and atherosclerosis." (PMID 36311201, 2022). "FABP4 plays an important role in macrophage inflammation and lipid metabolism in atherosclerosis." (PMID 36532833, 2022). "Our findings offer new insights into the mechanism of Hcy-induced macrophage inflammation, which may provide a novel FABP4-based therapeutic approach to atherosclerosis." (PMID 34725437, 2022). "Our previous studies have shown that FABP4 hypomethylation accelerates cholesterol accumulation in atherosclerosis induced by Hcy, suggesting that FABP4 may serve as a marker of atherosclerosis." (PMID 34725437, 2022). "Overall, our results demonstrate that C. albicans induces foam cell formation, inflammation, and MMP-9 expression in macrophages via the upregulation of FABP4, which may constitute a novel therapeutic target for treating C. albicans-induced atherosclerosis." (PMID 34829801, 2021). "Fatty acid–binding protein 4 (FABP4) and sterol regulatory element–binding protein 1 (SREBP1) have been implicated to have regulatory roles in numerous metabolic pathways, including lipid accumulation in the liver, T2DM, and atherosclerosis." (PMID 33809508, 2021).
atherosclerosis (continued). "While additional RT PCR analysis of respected genes could be helpful to support protein analysis in this study, further studies may be also warranted to verify if the blockade of FABP4 might be a promising therapeutic strategy for clinical atherosclerosis." (PMID 33287461, 2020). "Our findings support the key role of FABP4 as a potential therapeutic target for atherosclerosis." (PMID 33287461, 2020). "This study aimed to investigate the mechanistic role of FABP4 in atherosclerosis." (PMID 33287461, 2020). "Given that the interaction between MNCs and HCAECs may be essential for atherosclerosis, in this study, there are some new findings about the direct role of FABP4 in atherosclerosis." (PMID 33287461, 2020). "It was suggested that FABP4 may contribute to metabolic disorder and atherosclerosis through its actions in both macrophages and adipocytes in mice." (PMID 33287461, 2020). "As a result, FABP4 has been investigated as a potential biomarker of atherosclerosis." (PMID 32887447, 2020). "The impact of FABP4 on atherosclerosis seems to be attributed to its action in macrophages." (PMID 30857223, 2019). "Along with many other previous publications, people showed that FABP4 has a close relationship with metabolic syndrome, inflammation, atherosclerosis, obesity, insulin resistance, diabetes mellitus, hypertension, cardiac dysfunction, cardiovascular events, etc.." (PMID 30519272, 2018). "Importantly, FABP4 was established to increase the expression of inflammatory genes in human macrophages and to be involved in the development of atherosclerosis." (PMID 28886690, 2017). "Interestingly, the impact of FABP5 on reduction of atherosclerosis was even greater than that of FABP4." (PMID 28303004, 2017). "In conclusion, in contrast to FABP4, circulating FABP5 is associated with decreased CEC and carotid atherosclerosis, suggesting that FABP5 level is a regulatory factor of CEC and a potential biomarker for residual risk of atherosclerosis." (PMID 28303004, 2017). "Recent studies have indicated that FABP4 (fatty-acid-binding protein 4), an intracellular lipid chaperone of low molecular mass, plays an important role in the regulation of inflammation and atherosclerosis." (PMID 26823558, 2016). "Furthermore, genetic or chemical inhibition of FABP4 in murine models prevents atherosclerosis by reducing the endoplasmic reticulum (ER) stress response in macrophages." (PMID 24489659, 2014). "Mice that are double knockout for Apolipoprotein E (APOE) and FABP4 are protected from atherosclerosis compared to the APOE knockout alone; bone marrow transplantation studies have shown that this atheroprotective effect is mainly due to the absence of FABP4 in macrophages." (PMID 23122912, 2013). "Our findings indicate the involvement of FABP4 and leptin in the progression of atherosclerosis and plaque rupture, and suggest that down-regulation of PPAR/adipocytokine signaling within plaques may have therapeutic potential." (PMID 23122912, 2013). "We have identified FABP4 in leucocytes as a potential and easy accessible biomarker of atherosclerosis which could be of future clinical relevance." (PMID 23387955, 2013). "Furthermore, it has also been reported that serum FABP4 levels are positively correlated with carotid intima-media thickness as an index of atherosclerosis." (PMID 22121495, 2011). "We tested the hypothesis that FABP4 level predicts prognosis of patients with end-stage renal disease (ESRD), a group at high risk for atherosclerosis-associated morbidity and mortality." (PMID 22102888, 2011). "FABP4 has also been related to inflammatory responses within macrophages, and was recently also shown to regulate endoplasmatic reticulum homeostasis in these cells during atherosclerosis." (PMID 22174896, 2011). "Deficiency of FABP4 protected against atherosclerosis in apolipoprotein E- (ApoE-) deficient mice with or without high-cholesterol-containing western diets." (PMID 22121495, 2011).
atherosclerosis (continued). "In addition, we investigated the ability of different stimuli with relevance to atherosclerosis to regulate FABP4 expression in monocytes/macrophages." (PMID 22174896, 2011). "Involvement of FABP4 in atherosclerosis has also been indicated by clinical studies." (PMID 22121495, 2011). "FABP4 is a target for drug development in the treatment of atherosclerosis, diabetes, and asthma." (PMID 22046435, 2011). "Similarly, studies across various diseases, including atherosclerosis, type 1 diabetes, rheumatoid arthritis, and cancer, have identified FABP4 as a critical immune modulator that exacerbates disease pathology, primarily by enhancing macrophage proinflammatory activity." (PMID 39843629, 2025). "Therefore, FABP4 could affect the formation of foam cells and the accumulation of lipids and plays an important role in the development of atherosclerosis." (PMID 40824771, 2025). "Also, macrophages infected by P. gingivalis accumulate fatty acids, leading to an increase in FABP4 levels, which may initiate and/or contribute to the progression of systemic diseases like foam cell formation in atherosclerosis." (PMID 40002815, 2025). "Furthermore, upregulation of 15-LOX-1 is linked to the characteristic feature of early atherosclerosis and elevated synthesis of 13-HODE, which in turn enhances the expression of CD36 and FABP4 via PPAR-γ activation (13-HODE PPARγ-agonist) and triggers apoptosis." (PMID 39599599, 2024). "Thus, it would seem that inhibition of FABP4 function may be therapeutic for numerous prevalent diseases including diabetes, cancer, and atherosclerosis, and numerous small molecule inhibitors have been developed." (PMID 37207357, 2023). "FABP4 may also play a role in atherosclerosis through TLRs and other mechanisms." (PMID 36611783, 2023). "FABP-4 concentration has been reported to be independently associated with an alteration in carotid intima–media thickness, a marker of atherosclerosis, per one year; hence, it suggests that FABP-4 concentration could become a marker of atherosclerosis progression." (PMID 36144237, 2022). "FABP4 is secreted by macrophages and adipocytes and acts on multiple integrated pathways to regulate inflammation, promote proliferation and angiogenesis, and contribute to the pathogenesis of cancer and immunometabolic diseases (e.g., diabetes mellitus and atherosclerosis)." (PMID 35729106, 2022). "Therefore, FABP4 inhibition could be a potential therapeutic target in treating C. albicans-induced atherosclerosis." (PMID 34829801, 2021). "In addition, the fundamental FABP-4 was independently linked with modifications in carotid intima-media thickness (CIMT), which is a surrogate marker for atherosclerosis prediction, and in earlier studies, serum FABP-4 levels were shown to predict long-term cardiovascular events and mortality." (PMID 34680583, 2021). "It is clearly necessary to prospectively evaluate whether a change in the FABP4 value by direct inhibition, neutralization and/or blockade of unidentified receptors indeed reflects conditions of metabolic syndrome and atherosclerosis and predicts long-term cardiovascular outcomes in the future." (PMID 33597568, 2021). "Lack of FABP4 protects ApoE-deficient mice against atherosclerosis." (PMID 33287461, 2020). "Moreover, elevated ANXA2 and reduced level of fatty acid binding protein 4 (FABP4) may prevent atherosclerosis and cardiovascular diseases." (PMID 33424999, 2020). "FABP4 may be a therapeutic target for modulating atherosclerosis." (PMID 33287461, 2020). "In addition, Apolipoprotein E (ApoE)-deficient mice deficient in FABP4 exerted protective effects on atherosclerosis without affecting serum lipids or insulin sensitivity." (PMID 33287461, 2020). "In addition to be a marker of accelerated atherosclerosis, FABP4 may also be an important mediator in this process." (PMID 22174896, 2011).